ENSG00000212590
Synonyms: LOC124900247
Gene: Small nucleolar RNA gene on chromosome 7 (152,609,313 to 152,609,434, forward strand). Ensembl gene ENSG00000212590.
Gene Ontology:
Biological process: RNA processing
Cellular component: nucleolus
Homologues: Paralogues in human: SNORA26 (85% identical).